ALK (ALK receptor tyrosine kinase)
Diseases named in the same sentence as ALK in open-access papers (continued):
Sharing a sentence is not in itself a finding about the gene and the disease.
tumor (continued). "The ALK mutation was also undetectable in DNA from a further bone marrow trephine 4 months after first relapse and the CNS resection specimen, both of which had tumor cell contents of 85%–90%." (PMID 36029175, 2022). "Molecular analysis of tumor tissue identified an ALK p.R1275Q mutation with a MAF of 32.8%." (PMID 35565208, 2022). "However, ALK L1196M, a gatekeeper mutation that leads to resistance to crizotinib, showed little prevalence between tumor DNA and ctDNA (2% versus 22%, P=0.008), which implies that ctDNA can predict ALK-TKI resistance sometimes." (PMID 36387176, 2022). "In this study, we assessed whether the 5-mC scores reflected therapy-associated tumor DNA dynamics in the plasma of ALK-positive patients." (PMID 36461127, 2022). "Furthermore, previous study had shown that ICIs inhibited more effectively the tumor progression in NSCLC patients with KRAS mutations compared with ALK rearrangements." (PMID 36159860, 2022). "Array profiling of the three tumor samples showed that two of them had only numerical aberrations, whereas one sample displayed segmental alterations, including a gain at chromosome 2p, resulting in two copies of the ALK-mutated allele." (PMID 36140661, 2022). "In addition, crizotinib demonstrated growth inhibition and increased apoptosis of tumor cell lines with ALK fusion variants (EML4-ALK or NPM-ALK)." (PMID 35233056, 2022). "However, among those who were tested, EGFR mutation was found in 7% (30/423), ALK translocation in 1% (6/411), and PD-L1 tumor proportion score ≥ 50% in 39% (156/399)." (PMID 35621649, 2022). "Interestingly, in a patient resistant to lorlatinib ALK compound mutations were detected in two single CTCs and only one of them was present in the corresponding tumor biopsy." (PMID 36139444, 2022). "Similarly, cancers driven by ALK fusions or mutations can express specific ALK proteins, which act as neoantigens to elicit an organismal anti-tumor response." (PMID 36591504, 2022). "Tumor cells often develop acquired resistance to ALK inhibitors, resulting from secondary mutations in the patient’s kinase domain, gene amplification, and activation of alternative signaling pathways (e.g., EGFR, kit, IGF1R, etc.)and epithelial mesenchymal transformation." (PMID 35620280, 2022). "Interestingly, cooperative DNA methylation seems to be disturbed in ALK tumor cells, where we detected a loss of correlation and observed a higher methylation difference of neighboring CpGs, indicating a loss of collaboration between those sites." (PMID 33310759, 2021). "A copy number of > 12 copies of the ALK L1196M mutation could be observed in 1 μg of the whole DNA from tumor specimens with an epithelial phenotype." (PMID 33572278, 2021). "The high degree of spatial heterogeneity observed for SNVs in druggable target genes is exemplified by the ALK R1275Q mutation only being detected in 2 of 7 locations in the relapse tumour, the BRAF V600E mutation in only 3 of 7 locations and the FGFR1 N557K mutation in only 5 of 7 locations." (PMID 34815394, 2021). "In total, 41% of these tumours exhibit ALKF1174L mutations compared with other ALK mutations." (PMID 34769149, 2021). "The persistence or reappearance in tumors of an ALK rearrangement when on targeted treatment is sometimes associated to initial resistance or tumor progression and may be investigated using a new tissue biopsy or even a LB." (PMID 33467720, 2021). "A key question in the field is whether ALK mutations themselves can initiate tumour formation or whether other genomic alterations are required." (PMID 34769149, 2021). "Resistance mutations detected in loci other than ALK upon tumor progression." (PMID 34058070, 2021).
tumor (continued). "Our results suggest that a more careful analysis of ALK signalling activity in NB tumours in addition to ALK mutation genetic status may identify NB patients that would benefit from ALK TKI therapy." (PMID 33411331, 2021). "However, sequential use of ALK inhibitors can also lead to an accumulation of new ALK mutations in tumor cells." (PMID 34630126, 2021). "Similarly, resistance mechanisms, notably ALK mutations can be investigated with a LB on tumor progression in patients treated with ALK inhibitors." (PMID 33922637, 2021). "The origin of this tumor is unknown but some studies suggest that it might be a true neoplasm as some mutations on chromosome 2p23 of anaplastic lymphoma kinase (ALK) have been found to be related to this tumor." (PMID 30632123, 2020). "According to baseline NGS data, the median PFS in patients who had ALK rearrangement only, ALK rearrangement and concomitant tumor-suppressor gene mutations, and ALK rearrangement and concomitant oncogene mutations was 14.2, 10.9, and 4.9 months, respectively; (p = 0.0002)." (PMID 32974126, 2020). "Together with other mutations causing RAS/MAPK pathway activation, ALK mutations are also enriched in relapsed cases and ALK activation was shown to accelerate MYCN-driven tumour formation through hitherto unknown ALK-driven target genes." (PMID 31937834, 2020). "The effect of anti‐PD‐1/PD‐L1 monoclonal antibody in NSCLC patients with epidermal growth factor/anaplastic lymphoma kinase (EGFR/ALK) mutation was poor, which was related to the simultaneous reduction in T effector lymphocytes in the tumor body under the influence of the mutation." (PMID 32875727, 2020). "Indeed, molecules as ALK inhibitors were found to be appropriate in patients whose tumours harbour activating ALK mutations." (PMID 32336043, 2020). "Second, we were unable to control all factors which were associated with the level of tumor makers or ALK mutations, which may be due to introduced bias of retrospective design." (PMID 31489711, 2020). "In addition, the percentages reported largely depend on tumour histology, especially for ALK and EGFR mutations." (PMID 32236766, 2020). "Patients with SC/LH pattern could be hypothesized to have low levels of immune activation against tumor cells since the presence of the SC/LH pattern has been shown to be associated with low anti-ALK antibody titers at initial diagnosis." (PMID 32987765, 2020). "These pathological changes around the ALK-mutated tumor may result from the infiltration of tumor cells, suggesting the more invasiveness nature of ALK-rearranged tumors." (PMID 32266148, 2020). "The origin of this tumor is unknown but some studies call it a reactive process while a few of them suggest that it might be a true neoplasm as some mutations on chromosome 2p23 of anaplastic lymphoma kinase (ALK) have been found to be related to this tumor." (PMID 30632123, 2020). "Despite the small number of cases, their results indicated that the early reduction in the FDG uptake in the tumor mass after initiation of molecular agents could predict the subsequent tumor response in patients with EGFR-mutated or ALK-rearranged NSCLC." (PMID 33182575, 2020). "Signaling through the ALK-RAS-ERK1/2 MAPK pathway associates with NB tumor progression and relapse." (PMID 30866462, 2019). "lnc-GOLGA61-1 is upregulated in tumor samples harboring an ALK mutation or a MYCN amplification." (PMID 30952905, 2019). "Therefore, we cannot exclude that the ALK F1174L mutation was present in the primary tumor at a very low frequency and that this mutation has been positively selected during the establishment of the CLB-MA PT cell line." (PMID 31452835, 2019). "Moreover, tumours that contain anaplastic lymphoma kinase (ALK) fusion oncogene rearrangements, usually associated with never smokers, a younger age group and adenocarcinoma with signet or acinar histology, are sensitive to ALK-targeted therapies." (PMID 30889898, 2019).
tumor (continued). "Therefore, the proapoptotic activity of ALK-derived peptides, alone or in association with TKI, towards ALK-dependent tumor cells demonstrates their therapeutic potential." (PMID 30813562, 2019). "We have previously shown through ultra-deep sequencing that subclonal ALK mutations can be detected in NB tumours at diagnosis and that they are enriched at relapse, suggesting that ALK alterations may contribute to progression and a more aggressive disease." (PMID 30778092, 2019). "Therefore, in RMS both TFAP2B and ALK are functionally linked to PAX3/7-FOXO1 fusion positive tumours." (PMID 31493794, 2019). "ALK mutations were also detected at the I1171 and L1240 codons in one tumor each." (PMID 30778092, 2019). "This suggests that, at least in some patient tumors, ALK-mutated cells do not proliferate as a single clone and that potential cooperation between ALK-mutated and ALK-wild-type cells may be important for tumor growth and fitness." (PMID 31452835, 2019). "However, reports of a potential association between levels of ALK expression and prognostic factors such as age, tumour stage, MYCN status and DNA ploidy are conflicting and variable in methodology." (PMID 29642598, 2018). "In contrast, mutation and amplification of ALK within the same tumour is rare in NB." (PMID 29642598, 2018). "ALK alterations confer poorer prognosis for tumours in the intermediate- and high-risk categories." (PMID 29642598, 2018). "Now it is needed to investigate in detail the mechanisms of resistance related to the specific molecular alterations carried by the tumour and, thus, in our case, the drivers of and/or the mechanisms underlying the “de novo” and acquired resistance for ALK, ROS and RET fusion kinases." (PMID 29455670, 2018). "The mechanisms by which crizotinib exhibits its anti-tumor activity against various tumors harboring the mutation in ALK genes currently remain unclear." (PMID 28806414, 2017). "The trial was undertaken in an era before widespread testing for activating mutations of EGFR and ALK, histological differentiation and maintenance chemotherapy were standard practice and the newly introduced immune-checkpoint inhibitor for tumours with high PD-L1 expression." (PMID 28780466, 2017). "Possible explanations may be tumor subclonality, however technical/interpretation issues in the ALK diagnostic scheme cannot be excluded." (PMID 28415793, 2017). "More interestingly, we also observed genes involved in several important tumor‐associated pathways including the ALK pathway 15, 16, Lysine degradation 17 and ECM‐receptor interaction 18 showed dramatically higher levels of expression in HCC‐0010 cells compared with HepG2 cells." (PMID 29030911, 2017). "This tumor also harbored a secondary ALK mutation of unknown function and became resistant to a second generation ALK inhibitor." (PMID 28145866, 2017). "Also in this case, patients with EGFR or ALK genomic tumor mutations should have had disease progression on FDA-approved therapy for these aberrations prior to receiving atezolizumab." (PMID 28653990, 2017). "This might indicate a mixed tumor cell population or duplication of the fusion gene with gain of an ALK mutation in one of the two copies of the EML4-ALK fusion gene." (PMID 27045755, 2016). "Similarly, there was no statistical association between maximal percent change in tumor size and ALK FISH pattern (p=0.24)." (PMID 27769042, 2016).
tumor (continued). "The tumour resilience and the clonal evolution explain this ‘resistance mutations gene rating process’, and the scenario is more complicated taking into account also the non-ALK dominant escape phenomenon." (PMID 27433281, 2016). "Because EMT is commonly associated with tumor progression and metastatization or resistance to therapy, these findings have important implications for the biology and treatment of ALK-rearranged NSCLC." (PMID 27119231, 2016). "In NSCLC, primary resistance mechanism of ALK-fusion positive tumours has been mostly secondary mutations within the kinase domain of EML4-ALK, either when compromising drug binding (L1196M, G1269A) or when affecting enzyme conformation and activity (C1156Y, I1171T)." (PMID 25874976, 2015). "In patients with concurrent EGFR mutation and ALK rearrangement, the tumor response to certain TKIs may be inferior to historical data, depending on which genetic alteration is the major oncogenic driver." (PMID 26268359, 2015). "Thus, our results indicate that EML4-ALK-mediated stem-like phenotypes are dependent on the ALK activity and anti-tumor effects caused by crizotinib treatment at least partially are related with loss of stem-like potentials in EML4-ALK+ NSCLC cells." (PMID 26517679, 2015). "In IMT tumours, instead, acquired resistance to ALK inhibitors has shown to occur upon clonal selection of cells harbouring the F1174L activating mutation, in virtue of the important effects this substitution has on ALK tertiary structure." (PMID 25874976, 2015). "ALK encodes a receptor tyrosine kinase and is rearranged, mutated or amplified in several tumours." (PMID 25496518, 2014). "Therefore, our NCPC models allowed us to demonstrate the role of ALK-wt and the most frequent activating ALK mutations in NCPC in tumor initiation and in differentiation control." (PMID 24947326, 2014). "To date, the role of activating ALK mutations or ALK-wt overexpression in NB tumor initiation and progression remains unclear." (PMID 24947326, 2014). "The capacity of activating ALK mutations or ALK-wt overexpression to initiate tumor formation and progression may be dependent on their expression levels as well as on their temporal expression during sympathetic neuronal development and differentiation." (PMID 24947326, 2014). "However, the precise role of activating ALK mutations or ALK-wt overexpression in NB tumor initiation needs further clarification." (PMID 24947326, 2014). "Importantly, Hsp90 inhibitors are effective against tumour cells expressing ALK fusion proteins that possess mutations that render them resistant to the ALK inhibitor, Crizotinib." (PMID 22681779, 2012). "One study showed that the tumor cells of ALK+ S-ALCL could be associated with higher levels of apoptosis by chemotherapeutic drugs than those of ALK- S-ALCL." (PMID 22769020, 2012). "Although FISH can be performed on FFPE tumour specimens and detect multiple ALK fusion variants, there are various challenges related to the FISH technique, e.g. the break apart red and green signals indicating ALK rearrangements can be subtle and occasionally difficult to recognize." (PMID 22825000, 2012). "Remarkably, only a proportion of NB tumor samples with high level of ALK expression carries gene amplification and/or mutations, therefore, most of the ALK over-expression and its functional effects are uncharacterized and the underlying molecular mechanisms still undisclosed." (PMID 20957039, 2010). "Moreover, multi-omics analysis on both intrinsic and extrinsic immune landscapes revealed that the mutation of ALK could enrich infiltration of immune cells, enhance tumor immunogenicity, and improve immune responses." (PMID 41716637, 2025). "Current efforts are focused on designing ALK inhibitors that provide broader coverage of resistance-associated mutations while exhibiting enhanced CNS penetration, thereby addressing challenges such as compound mutations, bypass signaling activation, and tumor heterogeneity." (PMID 41614760, 2025).
tumor (continued). "The structural diversity, adaptive potential, and dynamic evolution of on-target mutations not only exemplify tumor cell remodeling under selective pressure from targeted therapy but also provide a precise framework for the rational design of next-generation, broad-spectrum ALK inhibitors." (PMID 41614760, 2025). "While the ALK fusion kinase clearly drives disease, it is not known if and how additional variants (co-mutations) coexisting with the ALK translocation may impact on tumor biology and explain the observed heterogeneity in clinical presentation, morphologic features, and response to treatment." (PMID 39478125, 2024). "Even patients who respond well to initial therapy with ALK inhibitors may experience tumor recurrence because of acquired resistance to these drugs via multiple mechanisms, including secondary ALK resistance mutations and tumor growth promoting molecular pathways." (PMID 36768562, 2023). "ALK-mutated NB may benefit from tumor-targeted therapies with ALK tyrosine kinase inhibitors (TKI)." (PMID 36765519, 2023). "As to paired CSF and tumor, a C797S mutation was detected both in CSF and tumor in 1 patient; 2 C797S mutations and 1 rare ALK fusion were detected only in tumor in 3 patients; Other than these, CSF-private and tumor-private mutations were still of unknown significance to disease progression." (PMID 35644609, 2022). "Thus, ALK ligands might still be important for tumor formation and progression, even in the case of activating ALK mutations." (PMID 35972154, 2022). "Until recently, several preclinical and clinical studies suggested that ALK rearrangement may be involved in innate and adaptive immunity through various pathways and is associated with T cell activation, cytokine release, and tumor immune escape." (PMID 35958559, 2022). "ALK TKIs also cause adaptive changes in tumor cells that favor their survival such as the upregulation of Bcl-2 and inhibition of autophagy; therapeutic strategies that target these changes may be effective in the treatment of ALK+ ALCL." (PMID 35211406, 2022). "Furthermore, elevated RET expression is observed in ALK-mutated primary NB tumor samples." (PMID 33921066, 2021). "Moreover, a previously unknown ALK mutation, namely G1202del, was outlined in two tumor specimens (8%)." (PMID 33572278, 2021). "Thus, ALK inhibition causes tumor cells to halt proliferation and die." (PMID 34272360, 2021). "However, several questions remain unanswered, including if single-agent crizotinib is optimal, or if a partner of ALK fusion kinase variants influences tumor response to crizotinib, and if next-generation ALK inhibitors are effective post-crizotinib resistance." (PMID 34722239, 2021). "Moreover, the detection of a specific ALK mutation in tissue or liquid biopsies cannot exclude presence of additional tumor clones with other ALK mutations in the same patient, which might be resistant to earlier ALK inhibitors." (PMID 33494549, 2021). "An additional case study reported more encouraging results: a 16-months-old patient with the novel ALK I1171T point mutation was treated with ceritinib monotherapy, which induced tumour cell differentiation and reduced tumour size, making it possible to resect the tumour." (PMID 34575503, 2021). "Therefore, we compared DMRs, defined over 1-kb tiling windows, between ALK tumor cells and Ctrl thymocytes to ENCODE ChIP-seq datasets for active enhancers including monomethylation of histone H3 lysine K4 (H3K4me1) and acetylation of histone H3 lysine 27 (H3K27ac) in murine thymi." (PMID 33310759, 2021). "To test whether the observed up-regulation of DNMT1 expression in ALK tumor samples is associated with deregulation of cell cycle–associated genes, we performed Western blot analysis using antibodies against c-MYC, CDK4/CDK6, cyclin D1, and the proliferation marker PCNA." (PMID 33310759, 2021).